IFNG (interferon gamma)
Diseases named in the same sentence as IFNG in open-access papers (continued):
Sharing a sentence is not in itself a finding about the gene and the disease.
autoimmune thyroid disease (28 papers, 2009 to 2025). Inflammatory disease of the thyroid gland due to autoimmune responses leading to lymphocytic infiltration of the gland. "Cytotoxic T-lymphocyte associated protein 4 (CTLA-4) inhibition worsened autoimmune thyroiditis in mice via the production of interleukin (IL)-2, interferon gamma, IL-10, and IL-13 cytokines." (PMID 34234669, 2021). "Subfertile women with autoimmune thyroid disease usually express increased levels of IFNγ from pro-inflammatory Th1 immune cells, along with lower IL-4 and IL-10 from Th2 immune cells compared with control patients without antithyroid antibodies." (PMID 35351031, 2022). "Autoimmune thyroid disease and IFNγ signaling were among the most highly enriched pathways in patients with high B cell infiltration." (PMID 34458583, 2021). "Since the aberrant expression of MHC-II molecules could be induced by IFNγ on thyroid follicular cells in autoimmune thyroiditis, it was postulated that IFNγ could be acting in a similar manner to induce this uncharacteristic expression in pancreatic β cells." (PMID 28959234, 2017). "Thyr-IFNγ transgenic mice can, therefore, provide a model to study chronic hypothyroidism, a feature not found in most animal models of autoimmune thyroiditis." (PMID 19924240, 2009). "Interestingly, the lack of LMP2 ameliorated the hypothyroidism seen in thyr-IFNγ transgenic mice, providing a novel explanation for the pathogenesis of hypothyroidism typically found in patients with autoimmune thyroiditis." (PMID 19924240, 2009).
glomerulonephritis (28 papers, 2008 to 2025). A renal disorder characterized by damage in the glomeruli. "Overexpression of T-bet in T cells of the Yaa mice promoted proteinuria and severity of glomerulonephritis and increased the expression of IgG2a and IFNγ, but inhibited the production of IL-4 and IL-5 in serum." (PMID 38164134, 2023). "MRL/lpr mice had lymph nodes shrunk, ameliorated glomerulonephritis, reduced expression of anti-dsDNA, IFNγ, and urine protein after 1 week treatment and were returned to the pre-treatment level 4 weeks later." (PMID 38164134, 2023). "Indeed, IFNγ has been shown to be involved in glomerulonephritis and other autoimmune phenomena in this strain." (PMID 23077665, 2012). "Metformin is a potential new therapy to reduce the levels of IFNγ and increase FOXP3 mRNA expression in SLE and in turn inhibits the development of glomerulonephritis." (PMID 34386197, 2020). "It has been reported that there were IL-17, IL-6, and interferon gamma (IFN-γ) up regulations in class IV glomerulonephritis SLE in comparison with non-nephritis SLE subjects in a sample of Iranian population." (PMID 33516274, 2021).
Hashimoto thyroiditis (28 papers, 2005 to 2025). An autoimmune disorder caused by the production of autoantibodies against thyroid tissue. "For people with severe autoimmune hypothyroidism, the Th1-related cells such as interferon gamma were secreted at a higher level compared to in those with mild autoimmune hypothyroidism." (PMID 35628903, 2022). "We have previously developed a mouse model of Hashimoto thyroiditis based on the chronic production of interferon-gamma (IFNγ) by the thyroid follicular cell via transgenesis." (PMID 19924240, 2009). "In Hashimoto thyroiditis, the serum levels of IL-2, IL-18, and IFNγ are higher in these patients." (PMID 40429402, 2025). "ROS were detected by the 2′,7′-dichlorodihydrofluorescein diacetate (CM-H2DCFDA) method in human thyrocytes treated with IL-1α and IFNγ to mimic Hashimoto’s thyroiditis (HT) and compared to non-treated cells." (PMID 33916948, 2021).
osteoarthritis (28 papers, 2008 to 2025). A noninflammatory degenerative joint disease occurring chiefly in older persons, characterized by degeneration of the articular cartilage, hypertrophy of bone at the margins and changes in the synovial membrane. "However, in conditions like osteoarthritis, the synovial fluid also contains a diverse range of compounds implicated in inflammation and catabolism, such as IL6, IFNγ, MMPs, TNFα and IL-1β." (PMID 39126115, 2024). "Similarly, the concentration of IFNγ in synovial fluid from patients with RA was reported to be higher than that in synovial fluid from patients with osteoarthritis (OA)." (PMID 35014010, 2022).
bacterial pneumonia (27 papers, 2010 to 2026). Acute infection of the lung parenchyma caused by bacteria (e.g., Streptococcus pneumoniae, Haemophilus influenzae, Chlamydia pneumoniae, Mycoplasma pneumoniae, and Legionella pneumophila). "To validate the correlation between Calhm6 and acute inflammation in humans, we found that mRNA levels of IFNG, TNFA, IL‐12, and Calhm6 in CD11b+ macrophages isolated from the peripheral blood of bacterial pneumonia patients were significantly elevated compared to healthy controls." (PMID 40999918, 2026). "Gr-1 has been used as a marker of IFNγ-producing rather than IL-17-producing γ/δ T cells in the setting of bacterial pneumonia, and CD11b+ γ/δ T cells are reported to produce IFNγ and to present exogenous antigens." (PMID 34675929, 2021).
chronic hepatitis C (27 papers, 2006 to 2024). "Chronic hepatitis C caused by the hepatitis C virus and intrahepatic interferon-gamma (IFN-γ), which causes increases in CXCL10 production by the sinusoidal endothelium and hepatocytes, subsequently attracting T-cells expressing CXCR3 to the liver." (PMID 38816794, 2024). "In addition, the IFNγ expression in PBMCs was associated with inflammatory activity in chronic hepatitis C patients, and serum IFNγ levels were elevated in fulminant hepatic failure patients." (PMID 38907339, 2024). "Chronic hepatitis C infection (HCV) activates a systemic cell-mediated immune response characterized by the production of IFNγ and an innate immune response addressed by the activation of TLR signaling." (PMID 33917265, 2021). "IFNγ alone has been shown to be without benefit in the treatment of chronic hepatitis B or chronic hepatitis C and to be poorly tolerated when combined with IFNα treatment." (PMID 27713294, 2010).
nephritis (27 papers, 2006 to 2025). Inflammation of renal tissue. "Recent data suggest that IFNγ contributes specifically to nephritis, as IFNγR1-deficient Sle1b.Yaa mice present with reduced glomerular nephritis scores compared to both B6.Sle1 and Sle1.Yaa mice." (PMID 35055071, 2022). "It was characterized by a distinct biomarker profile (including higher IFNγ levels), earlier disease onset, and more nephritis and was the only cluster associated to HLA-DRB1*15, indicating that we may be dealing with a distinct SLE subset." (PMID 38460182, 2025). "Chronic IFNγ overproduction induces hepatoxicity; IFNγ also plays a crucial role in the development of nephritis." (PMID 34224653, 2022). "In NZBxW F1 mice, development of autoantibody and nephritis were prevented by IFNγ receptor deletion, and treatment with anti-IFNγ delayed onset." (PMID 25285625, 2014). "Whether Klotho inhibits nephritis by blocking IFNγ-targeted proteins and IFNγ downstream signaling remains unclear." (PMID 37213666, 2023). "Furthermore, levels of IL-17, IL-10 and IFNγ have been found to be increased in SLE patients, the latter predominantly in patients with active nephritis." (PMID 35055071, 2022). "As peripheral blood IFNγ levels are elevated in SLE patients and have been shown to correlate with nephritis, this could be of potential relevance." (PMID 18811944, 2008).
squamous cell carcinoma (27 papers, 2008 to 2026). A carcinoma arising from squamous epithelial cells. "In line with our observation, previous studies have shown that PER1 is able to inhibit Akt/mTOR signalling, although in squamous cell carcinoma, and plays a role in the regulation of cytokine expression, such as IFNG, in NK cells." (PMID 35143696, 2022). "In conclusion, EGFR signaling in squamous cell carcinoma cells from the head and neck represses the production of several IFNγ/TNFα-induced T-cell attracting chemokines." (PMID 30192802, 2018). "Thus, the EGFR-mediated suppression of IFNγ/TNFα induced chemokine expression in squamous cell carcinoma cells from the head and neck primarily is mediated by both the MEK and JNK signaling pathways." (PMID 30192802, 2018). "For this study, a cell model that was engineered in our previous publication is used to investigate the role of IFITMs—SiHa cells originating from squamous cell carcinoma of the cervix which express IFITM1 and IFITM3 at detectable endogenous levels with a higher expression upon IFNγ stimulation." (PMID 36008984, 2022).
colon adenocarcinoma (26 papers, 2003 to 2025). "To determine the relevance of our findings in human Colon adenocarcinoma, we assessed IFNγ/STAT1/IRF7/IFI35/CD8 expression with Timer database." (PMID 37380972, 2023). "NLRC5 was expressed to varying degrees in healthy gut tissue and most highly in colon adenocarcinoma, and was inducible by IFNγ in HCT116 cells." (PMID 29928061, 2018). "In another study, a single recombinant adenovirus with both interferon-gamma (IFN-γ) and Ii-RGC (rAV/IFN-γ/Ii-RGC) genes efficiently induced the MHC Class II+/Ii- phenotype in MC-38 colon adenocarcinoma cells and Renca tumors." (PMID 32079263, 2020). "This property of the flavonoid was shown in rats, counteracting the effect of a high-fat diet, and in human colonic adenocarcinoma (Caco-2) cells treated with ethanol, polybrominated diphenyl ether, and tumor necrosis factor-alpha (TNF-α) and interferon-gamma (IFN-γ)." (PMID 38998064, 2024).
food allergy (26 papers, 2009 to 2025). Gastrointestinal disturbances, skin eruptions, or shock due to allergic reactions to allergens in food. "Th1 and Th17-immunity associated cytokines (IL-12, IL-23, IFNγ, IL-17), considered by some to be contributors to oral tolerance in food allergy, reveal a markedly different picture from that seen for type 2 immunity responses." (PMID 23071516, 2012).
inflammatory skin disease (26 papers, 2013 to 2025). Inflammatory skin disorders covers a broad category that includes many conditions ranging in severity, from mild itching to grave medical health complications These disorders are common in people of all ages and races. "ACD is an inflammatory skin disease, driven by a complicated cell-cell network mediated by several T cell-associated cytokines, including Th1 cytokine IFNγ, Th2 cytokines IL4, IL13, and Th17 cytokine IL17." (PMID 39213029, 2024). "In patients with inflammatory skin disorders, these TH22 cells were found to produce only IL-22 but not IFNγ, IL-4, or IL-17." (PMID 23460846, 2013).
meningitis (26 papers, 2013 to 2025). A disorder characterized by acute inflammation of the meninges of the brain and/or spinal cord. "have also found inflammatory markers elevated in the CSF during VZV-related meningitis, including interferon gamma, interleukins IL-6, IL-8, IL-10, IL-17F, IL-1RA, chemokines CXCL-9, CXCL-10, CCL-2 and G-CSF." (PMID 40416981, 2025). "Compared to other types of meningitis, several cytokines such as interferon gamma (IFN-γ), tumor necrosis factor alpha (TNF-α), interleukin (IL)-1β, IL-6, and IL-10 are upregulated in the CSF of TBM patients." (PMID 38047697, 2024). "Recombinant interferon gamma has been tried as an additional modality in patients with cryptococcomas and/or severe meningitis who were unresponsive to prolonged courses of multiple antifungal drugs." (PMID 31382367, 2019). "It is therefore conceivable that the relevance of IFNγ production in the pathogenesis of meningitis may be serotype-specific or host-specific." (PMID 27009189, 2016). "Of the 13 measured, 11 (GM-CSF, IFNγ, IL-1α, IL-1Β, IL-2, IL-4, IL-6, IL-10, IL-12, IL-18, and TNF-α) exhibited higher concentrations in the saliva of pigs with meningitis and S. suis infection." (PMID 40284818, 2025). "When a panel of cytokines (including GM-CSF, IFNγ, IL-1α, IL-1β, IL-1ra, IL-2, IL-4, IL-6, IL-8, IL-10, IL-12, IL-18, and TNF-α) was measured in saliva from healthy pigs and in pigs with meningitis and S. suis infection, upregulation of several cytokines was observed in the diseased animals." (PMID 40284818, 2025).
Miscarriage (26 papers, 2014 to 2026). A pregnancy that ends at a stage in which the fetus is incapable of surviving on its own, defined as the spontaneous loss of a fetus before the 22th week of pregnancy. "The increased production of the cytokines IFNγ and TNFα by dNK cells and placental macrophages is associated with the development of miscarriage." (PMID 35216502, 2022). "TNF -238G > A, TNF -308G > A, IL1B -511 T > C, IL1B 3954C > T, IL6 -174G > C, IL6 -634C > G, IL10 -1082A > G and IFNG 874A > T polymorphisms were genotyped on 775 women with idiopathic recurrent miscarriage and 805 healthy parous control women." (PMID 29017513, 2017). "In addition, according to the literature data, the reduced production of IL-10 and IFNγ cytokines in the decidua is associated with miscarriage." (PMID 40332223, 2025). "Thus, the IFNG gene may cause maternal foetal Th1/Th2/Th17/Treg imbalance by regulating the release of IFN-γ, thereby increasing the risk of miscarriage." (PMID 34421922, 2021). "At the same time, it is known that the secretion of TNFα, as well as IFNγ, by dNK cells is increased in spontaneous miscarriage." (PMID 35216502, 2022). "The changes in individual expression of TNFa and IFNg, however, were more marked in the implantation failure population, wih IFNg being potentially more resistant to change in those with miscarriage." (PMID 29507746, 2018).
renal fibrosis (26 papers, 2014 to 2026). A final common manifestation of a wide variety of chronic kidney diseases characterized by glomerulosclerosis and tubulointerstitial fibrosis. "In models of renal fibrosis, Tregs induced by mesenchymal stem cells (MSCs) pretreated with interferon-gamma (IFN-γ) were found to significantly decrease fibrosis and improve kidney function." (PMID 40948794, 2025). "Soluble klotho also inhibited TGF-β-induced renal fibrosis and metastasis and blocked the levels of the inflammatory proteins TNFα and IFNγ." (PMID 31581134, 2019). "Recently, we studied anti-fibrotic effects of IFNγ and PEGylated IFNγ (PPB-PEG-IFNγ) targeted to PDGFRβ-expressing myofibroblasts in an animal model of renal fibrosis." (PMID 26112172, 2015). "Drug Discovery Collection: TGFβ induces renal fibrosis in ex vivo cultured precision-cut kidney slices, which can be attenuated by IFNγ." (PMID 26112172, 2015). "The aim of this study was to validate the precision-cut kidney slice (PCKS) model for the development of renal fibrosis and to evaluate the potential anti-fibrotic effects of IFNγ and an IFNγ conjugate in this ex vivo model." (PMID 26112172, 2015). "Recently, it was shown that IFNγ could enhance the immunosuppressive properties of mesenchymal stem cells in a model of experimental renal fibrosis." (PMID 37038186, 2023). "Ifnγ, also highly induced in NI-13, is protective against renal injury induced by arsenite by modulation of detoxification pathways and experimental renal fibrosis following chemotherapeutic exposure, explained by increasing the viability of renal tubular cells." (PMID 27955686, 2016). "As yet, it is unknown whether precision-cut kidney slices (PCKS) can be used to study the development of renal fibrosis and to screen the efficacy of anti-fibrotic compounds, e.g. IFNγ." (PMID 26112172, 2015). "IFNγ could be a useful therapeutic target to attenuate the development of renal fibrosis." (PMID 26112172, 2015). "Macrophage-related cytokines facilitate cystic renal cell proliferation or renal fibrosis in ADPKD via TGF beta, IL-17 TNF alpha, or IFNγ." (PMID 39768851, 2024).
rheumatic diseases (26 papers, 2010 to 2025). "IIgG4-RD is characterized by the presence of auto-reactive clones of enlarged cytotoxic T-lymphocytes (CTLs) that produce interferon-gamma that have also been observed in various other autoimmune and rheumatic disorders." (PMID 39751976, 2025). "We previously observed dynamic changes in IFNγ levels from QFT-GIT test performed in patients with rheumatic diseases during the initial 18 months of treatment with biological therapy." (PMID 29777119, 2018). "Given the similarity of pathophysiology of primary and secondary HLH, currently ongoing and future studies will contribute to define the precise role of this IFNγ neutralizing antibody in controlling HLH manifestations occurring in the context of rheumatologic disorders or malignancies." (PMID 33424859, 2020). "Marked increase of proinflammatory cytokines including IL-1, IL-6, IL-18, TNFα, IFNγ, ferritin and ST2 during MAS attacks portrayed a significant systemic inflammation in patients with various rheumatic diseases, particularly sJIA28,44–47." (PMID 34099791, 2021). "Indeed, we found that pSTAT1 levels in unstimulated and IFNγ-stimulated monocytes are sensitive and specific in discriminating sHLH/MAS patients not treated with glucocorticoids at sampling from patients with active sJIA and other rheumatic diseases." (PMID 33815425, 2021).
triple-negative breast carcinoma (26 papers, 2019 to 2025). An invasive breast carcinoma which is negative for expression of estrogen receptor (ER), progesterone receptor (PR), and human epidermal growth factor receptor 2 (HER2). "In triple-negative breast cancer, high expression of IFNG was found to be associated with better disease-free survival." (PMID 31967976, 2020). "As an important effector cytokine for cancer immunity, IFNγ also has prognostic and predictive significance in basal-like or triple-negative breast cancer, arguing for a protective effect of IFNγ-mediated immune responses by vaccination." (PMID 34638367, 2021). "However, we observed decreased NQO1 protein levels upon IFNγ treatment in three of five triple-negative breast cancer (TNBC) cell lines tested (MDA-MB-231, Hs578T, and MDA-MB-436)." (PMID 34083537, 2021). "Since MDA-MB-231, MDA-MB-468, and 4T1 cells are models for triple-negative breast cancer (TNBC), these findings strongly indicate that TPST2 regulates IFNγ signaling, at least in TNBC." (PMID 39095793, 2024). "To identify potential T-cell targets for Triple-Negative Breast Cancer (TNBC) vaccination, we examined the effect of the pro-inflammatory cytokine interferon-γ (IFNγ) on the transcriptome, proteome, and immunopeptidome of the TNBC cell line MDA-MB-231." (PMID 33968037, 2021). "This study presents a comprehensive bioinformatics-based investigation into the ferroptosis landscape of triple-negative breast cancer (TNBC), with a central focus on the role of interferon-gamma (IFNG) as a potential prognostic marker and modulator of ferroptotic signaling." (PMID 40868287, 2025).